CD4 (CD4 molecule)
Diseases named in the same sentence as CD4 in open-access papers (continued):
Sharing a sentence is not in itself a finding about the gene and the disease.
viral infection (continued). "The vast majority of T cell responses to HLA class I-restricted SARS-CoV-2-specific EC were mediated by both CD8+ and CD4+ T cells, which is an often described phenomenon especially in viral disease." (PMID 33723016, 2021). "We previously generated monoclonal antibodies (mAbs) against olive flounder (Paralichthys olivaceus) CD4 T cells, CD4-1 and CD4-2, and used these to describe the olive flounder’s CD4 Tcell response during a viral infection." (PMID 33467734, 2021). "This in turn leads to differentiation of CD4+ T-cells into Th1 phenotypes to promote pro-inflammatory responses, especially during viral infection." (PMID 34790206, 2021). "CD4+ T cells generated in response to viral infection are mainly of the T helper 1 (Th1) phenotype and produce large amounts of IFNγ, TNFα and IL-2 and express T-bet when exposed to IL-12 and type I interferons." (PMID 34066322, 2021). "MBL can also selectively bind to HIV-1-infected cells and inhibit viral infection of CD4+ T cell lines." (PMID 34154540, 2021). "In general, in response to viral infection, several subsets of antigen-experienced CD4+ T cells are generated from naive CD4+ T cells to aid virus elimination." (PMID 34066322, 2021). "But in some viral infections, this ratio is destroyed, and the CD4:CD8 ratio is inverted <1:1, indicating a serious immune disorder." (PMID 33350432, 2021). "As previously reported, the kinetics of plasma viral load and CD4 T-cell counts in blood evidenced the viral infection and a comparable course of the disease in these macaques." (PMID 33572146, 2021). "While this assumption is generally valid for acute viral infections, there are some notable differences, particularly in FoxP3 and CD4 expression levels." (PMID 34944938, 2021). "Tetherin + DCs are more vigorously stimulated virus-specific CD4 + T cells compared to Tetherin KO DCs ex vivo even though similar virus infection levels." (PMID 34753980, 2021). "Since L-selectin facilitates HIV adhesion and infection of CD4 T cells, inhibition of its shedding was predicted to enhance the viral infection, presumably increasing the mode of superinfection." (PMID 34659153, 2021). "Cytotoxic CD4+ cells were previously identified and therapeutically used in murine models of cancer and colitis and in healthy humans and human viral infection." (PMID 33879187, 2021). "Multiple lines of evidence in the literature support the important role of CD4 T cells in promoting CD8 T cell function during viral infection and in rescuing CD8 T cells from exhaustion in the context of chronic infection." (PMID 33901266, 2021). "Unlike tetherin and TIM members, however, L-selectin is abundantly expressed on primary CD4 T cells, and inhibition of L-selectin shedding presents a more efficacious target for suppressing the viral infection." (PMID 34659153, 2021). "In the lung, CD4+ TRMs contributes to a delayed infection, providing immunity against viral infection, and is necessary for CD8+ TRM generation." (PMID 34445713, 2021). "CD4+ CTLs play an important role in chronic antiviral responses and contribute directly to the containment of viral infection." (PMID 34950144, 2021). "We also identified relatively high magnitude CD4 T cell responses against the virus that localized to the lung 21 days after viral infection." (PMID 34929014, 2021). "During acute viral infection, bifurcation of effector CD4+ T cells into TFH cells or TH1 cells can be observed as early as the second to third division." (PMID 33637761, 2021). "These cytolytic CD4+ lymphocytes are more frequent in DENV immune-donors that carry a protective HLA-DR allele, which would lead to greater control of viral infection in vivo." (PMID 33525328, 2021). "Distinct from reports of virus infection, we found that IL-10 was expressed by conventional, Foxp3-negative effector CD4 T cells and functioned in a B cell-intrinsic manner only during the first 96 hours of Plasmodium infection to support humoral immunity." (PMID 33529242, 2021).
viral infection (continued). "Tec kinase signalling pathway has also critical role in response to viral infection and is essential for differentiation and development of CD4+59 and CD8+ T cell." (PMID 34475461, 2021). "In the absence of ex vivo stimulation, IL-2 production by naive Foxp3− CD4+ T cells was also observed in early life after viral infection, and IL-2+ cells expressed more IL-2 per cell than those from adults." (PMID 34665220, 2021). "Susceptible SJL mice preimmunized with viral peptides or UV-inactivated TMEV prior to viral infection preferentially mount protective CD4+ T cell (Th1) type responses, which in turn subsequently prevent the development of pathogenic Th17 cell responses." (PMID 34067536, 2021). "Here we show that viral infection attenuates the expression of genes related to lipid metabolism in murine CD4+ T cells, which in turn increases the expression of antiviral genes." (PMID 34188173, 2021). "CD4+ T cells are increasingly recognized as playing an essential role in the control of chronic viral infections." (PMID 33430234, 2021). "With this approach, we observed a short-lived acute CD4+ cell recruitment immediately following viral infection followed by later, sustained CD8+ cell recruitment (out to at least 28 days post-infection)." (PMID 33376758, 2021). "Excessive levels of cytokines such as IL-6 and IL-1β produced via TLR3 signaling prior to viral infection hinder the induction of protective IFN-γ-producing CD4+ and CD8+ T cell populations." (PMID 34067536, 2021). "It has been reported that peptide immunization or ZIKV infection-elicited CD4+ T cell responses are necessary for protection against virus infection and further viral clearance in primary infection." (PMID 33810028, 2021). "The early preservation of these high-affinity CD8 T cells through decreased virus replication, augmented CD4 help, and enhanced costimulatory signals has important implications for virus control and immune restorative therapies during chronic viral infections." (PMID 34206262, 2021). "We next assessed CD4 utilization by the sensitivity of viral infection to DARPin D23.2, an antagonist that targets cellular CD4 and blocks its interaction with gp120." (PMID 34627310, 2021). "CD4+ T cells in neonates have higher rates of cell metabolism, proliferation and “activated” cell phenotypes making them prime candidates for viral infection." (PMID 34793582, 2021). "For viral infection, IL-6 signal is very important to control virus expansion by stimulating CD4+ T cells, leading to germinal center activation and improving antibody response in mice." (PMID 34738866, 2021). "Collectively, these results suggest that HCV infection deregulates the expression of multiple mitochondria-localized proteins, which contributes to mitochondrial compromise in CD4 T cells during viral infection." (PMID 34956192, 2021). "The interferon signaling pathway that is essential for increased cellular resistance to viral infection was found activated at 5 dpv in CD4+, CD8+, and CD14+ cells of both species." (PMID 33785572, 2021). "We also noticed elevated HLA-DR-positive CD3+ cells in infants with LOS and a higher CD4/CD8-ratio in infants with viral infection as compared to healthy controls." (PMID 34512621, 2021). "Viral infection induces the early bifurcation of CD4 T cells into Th1 and T follicular helper (Tfh) cells." (PMID 33684030, 2021). "We also noticed elevated HLA-DR-positive CD3+ cells (activated T lymphocytes) in infants with LOS and a higher CD4/CD8-ratio in infants with viral infection as compared to healthy controls." (PMID 34512621, 2021). "During acute viral infection, effector CD4+ T cells’ commitment to the TFH lineage or TH1 lineage emerges before the initiation of GCs12." (PMID 33637761, 2021). "CD4+ T cells can differentiate into Th1 and Th2 cells that have critical roles in immune responses including clearing virus infection and regulating immunoglobulin isotype switching." (PMID 34783655, 2021).
viral infection (continued). "Of note, the CD8 T‐cell population showed much higher activation and Ki‐67 expression than the CD4 T cells, suggesting its prominent role in response to viral infection." (PMID 33784417, 2021). "During acute viral infection, CD4 + T cells assist in the activation of CD8 + T and B cells to clear the virus." (PMID 34950144, 2021). "Very few published data sets compare antigen-specific antibody, B cell, CD8+ T cell, and CD4+ T cell memory to an acute viral infection in the same individuals." (PMID 33408181, 2021). "A recent study has confirmed SARS-CoV2 can directly infect and replicate in CD4 T helper cells via viral infection tests of isolated healthy human peripheral blood samples, and by confirming presence of SARS-CoV2 RNA in COVID patients." (PMID 33305306, 2021). "The memory T cell half-lives observed over 6+ months PSO in this cohort (~125-225 days for CD8+ and ~94-153 days for CD4+ T cells) were comparable to the 123 days t1/2 observed for memory CD8+ T cells after yellow fever immunization." (PMID 33408181, 2021). "Our set of MHC class II-restricted TCRs represents an important tool for elucidating CD4+ T cell help in viral infection with potential benefit for T cell therapy." (PMID 34853796, 2021). "High levels of FoxP3+CD4+ T cells are present in the CNS of virus-infected mice as early as 3 d after viral infection." (PMID 34067536, 2021). "Consistent with this, recent studies showed ineffective CD4+ T cell or CD8+ T cell responses in viral infection following microglial depletion with PLX5622." (PMID 34311763, 2021). "Our data indicate that the small intestine has the potential to be a primary site for viral infection and that CD4+ T cells are the primary target cells 96 hours after viral exposure." (PMID 34793582, 2021). "During some viral infectious diseases, exhausted CD4+ Tcells reveal diminished proliferative capability and lack of multifunctional cytokine response, particularly decreased production of IL‐2, which results in disease progression." (PMID 34499819, 2021). "Virus infection also upregulated CXCR3 expression in CD4+ T-cells in MLN, as shown by the expansion of CXCR3+ (Student’s t-test, p = 0.002), CXCR3+CCR4+ (Student’s t-test, p = 0.007) and CXCR3+CCR5+CCR4+ CD4+ T-cell subsets (Student’s t-test, p = 0.001)." (PMID 34685494, 2021). "In the context of inflammation and viral infection in healthy individuals, CD56bright NK cells suppress autologous CD4 T cell proliferation through direct cytotoxicity, dampening the inflammatory process." (PMID 34685542, 2021). "Cytotoxic CD4+ T-cells have mostly been described in situations of chronic antigen exposure such as persistent viral infection and cancer." (PMID 34882759, 2021). "Mock control of 6 D-, 2 W-, and 6 W-aged mice showed substantial increase of lung IFN-γ+ CD4+ T cells as a result of live virus infection." (PMID 34063125, 2021). "Tregs generated in the thymus and in the periphery constitute a CD4+ T cell subset dedicated to the control of immune activation, and as such play a key role in limiting immunopathological damage in viral infections." (PMID 33430234, 2021). "Once viral infection is controlled, CD4 TRM express CCR5 and are found around the epithelial layer in human oral mucosal tissues." (PMID 34959486, 2021). "Animal model studies have confirmed the induction of cytotoxic CD4+ T cells in a variety of viral infections, often with a preferential localization in the lung or gut mucosa." (PMID 33430234, 2021). "Along that line, the importance of CD4+ T cells in fighting viral infections and tumor diseases also implies their benefit for immunotherapy and potentially for adoptive T cell therapy, including treatment of CHB- and HBV-induced HCC." (PMID 34853796, 2021). "Induction of CD4 T follicular helper (Tfh) cells is important for antibody responses to viral infections." (PMID 33483492, 2021).
viral infection (continued). "In fact, early functional rescue of CD4 T cells during persistent viral infection by the administration of antiviral therapy still leads to CD8 T cell exhaustion." (PMID 34206262, 2021). "CD4 T follicular helper (Tfh) cells are important for the generation of durable and specific humoral protection against viral infections." (PMID 32818217, 2020). "High levels of FoxP3+CD4+ T cells were found in the CNS early in viral infection (3 dpi) and persisted throughout the infection." (PMID 33086489, 2020). "The majority of CD4+ T cells produced in response to viral infection are of the T-helper 1 subtype, producing IFN-γ and expressing the transcription factor T-bet." (PMID 32509591, 2020). "These functions of Egr2/3 in PD-1high MP CD4 T cells are required for the maintenance of a diverse repertoire of MP T cells, which is important for adaptive responses against viral infection." (PMID 32709717, 2020). "Here, we found that EZH2 is integral for virus-specific CD4 T cell expansion in a mouse model of acute viral infection." (PMID 32999031, 2020). "TFH memory CD4 T cells are largely derived from CD25low effector CD4 T cells generated during early cell divisions after viral infection, as are TH1 memory cells." (PMID 32899486, 2020). "Some are highly compatible with an uncontrolled viral infection, as exemplified by an increase (2–3-fold) of most differentiated effector memory CD4+ and CD8+ T cells." (PMID 32829467, 2020). "In this study, we adoptively transferred naive VP2-specific TCR-Tg CD4+ T cells into syngeneic susceptible SJL mice and monitored the development of the disease and the activation and proliferation of CD4+ T cells during the early stages of viral infection." (PMID 33086489, 2020). "We also examined the functional activity of the CD4-1 and CD4-2 cells in vivo in response to a viral infection, with the numbers of both types of CD4 T cells increasing significantly during the virus infection." (PMID 32545330, 2020). "When stratified by both viral infections, a further moderate decline in median frequency of cervical CD4 T cells was observed in HIV+HPV+ women compared to HIV+HPV- women (median %: 22.7 vs 32.8, p = 0.041)." (PMID 33007050, 2020). "This micronutrient is also found to play roles in viral infection protection due to altering monocytes/macrophages cytokines production and CD4+ T cells proliferation." (PMID 33230422, 2020). "Together, these results indicated that impaired mTOR activity contributes to the poor expansion of virus-specific CD4 T cells devoid of EZH2 protein upon viral infection." (PMID 32999031, 2020). "As CD4+ T cells play important roles in clearing many viral infections, several mechanisms by which viruses inhibit MHCII antigen processing and presentation have been described." (PMID 32745153, 2020). "In co-culture experiments of Tregs and conventional CD4 T cells, Tregs reduced DC mediated viral infection of CD4 T cells." (PMID 32714317, 2020). "Here, we also found that EZH2 is indispensable for mTOR signal activation in CD4 T cells during acute viral infection." (PMID 32999031, 2020). "CD4 T cells play a critical role in attenuating or suppressing overactive innate immune responses during viral infection to maintain self-tolerance and immune homeostasis." (PMID 33195212, 2020). "During acute viral infections, systemic infections, and in the tumor microenvironment NK cells can dysregulate CD4+ and CD8+ T cell responses promoting pathogen and tumor persistence and immune exhaustion." (PMID 32733814, 2020). "The similar transcriptional profiles and impairments in proliferation seen in both Egr2/3−/− PD-1high MP CD4 T cells and Egr2/3−/− effector T cells responding to viral infection indicates a general function of Egr2/3 is to support T-cell proliferation." (PMID 32709717, 2020). "The genetic ablation of EZH2 leads to impaired cellular metabolism and, consequently, poor CD4 T cell response to acute viral infection." (PMID 32999031, 2020).
viral infection (continued). "These CD4+ cytotoxic T lymphocytes (CD4+ CTLs) have been identified in patients with viral infections and contribute to antiviral immune responses." (PMID 32102981, 2020). "As we known, viral infection can result in a decreased CD4+ T cells, which actually plays an essential role in the defense against fungal infections." (PMID 33537328, 2020). "Consistent with this view, the highly successful live yellow fever vaccine YF-17D activates multiple PRRs that collectively define the cytokine profile and magnitude of both CD4 and CD8 T cell responses as well as antibody responses." (PMID 33104760, 2020). "Egr2/3 not only control inflammation but also support the homeostatic proliferation of PD-1high MP CD4 T cells and their fitness for adaptive responses to viral infection demonstrating an important function of PD-1high MP CD4 T cells in adaptive immunity." (PMID 32709717, 2020). "The CD4 T cell response to viral infection is the summation of antigen-induced epigenetic reprograming and metabolic shifts." (PMID 32999031, 2020). "Conversely, previous studies on viral infections in swine have shown that the CD4+ Tcm subset was capable of IFN-γ, TNF-α and/or IL-2 production." (PMID 33584671, 2020). "We chose this time point because IFN responses peak early in viral infections and innate instruction of CD4+ T cells and B cells is thought to occur at that time as well." (PMID 33104760, 2020). "Next, we sought to explore the role of EZH2 in the late differentiated phase/memory phase of the CD4 T cell response to acute viral infection." (PMID 32999031, 2020). "SIV or SHIV infection of macaques reflects human infection in regard to cell tropism of viral infection, progressive depletion of CD4+ T cells and development of opportunistic infections typical of AIDS." (PMID 32650790, 2020). "The CD4 T cell response is critical in curtailing viral infection or eliciting efficacious viral vaccination." (PMID 32999031, 2020). "We next explored the transcript levels of MHC class I and II molecules in antigen-presenting cells (APCs) to evaluate population and temporal dynamics of antigen presentation to CD8+ and CD4+ T cells following viral infection with JHMV." (PMID 32999036, 2020). "CD4+ T cells orchestrate the response to acute and chronic viral infections by coordinating the immune system." (PMID 33384690, 2020). "In response to acute viral infection, virus-specific CD4 T cells differentiate into either CXCR5-positive follicular helper T (TFH) cells or CXCR5-negative TH1 cells (16, –, 18)." (PMID 32999031, 2020). "This is particularly interesting since during infection Th1 CD4+ T cell response are a primary response fundamental to control viral infection and Th and Treg cells differentiate in parallel phenotypes in response to inflammatory signals." (PMID 32984065, 2020). "Id2 is a key regulator of effector CD8 T cell differentiation and maintenance in vivo and has also been shown to promote the differentiation of IFN-γ-producing CD4+ T (so-called Th1) cells upon viral infection." (PMID 32002568, 2020). "These include the production of specific antibodies, CD4+ T-cell and cytotoxic T-cell activation which play a major role in resolving viral infections." (PMID 33425136, 2020). "CMVR accounts as the most common opportunistic viral infection in HIV patients which often manifests in CD4+ counts lower than 50/μl." (PMID 32588149, 2020). "IMPORTANCE The CD4 T cell response is critical in curtailing viral infection or eliciting efficacious viral vaccination." (PMID 32999031, 2020). "In conclusion, our present study demonstrates that the epigenetic regulator EZH2 is integral for CD4 T cell expansion during acute viral infection." (PMID 32999031, 2020). "CD4+ T cells play important roles in controlling bacterial and viral infections through the production of cytokines (predominantly secretion of IFN-γ by Th1 cells) and by stimulating B cells to produce antibodies (Tfh cells)." (PMID 32983171, 2020).